KIT (KIT proto-oncogene, receptor tyrosine kinase)
Diseases named in the same sentence as KIT in open-access papers (continued):
Sharing a sentence is not in itself a finding about the gene and the disease.
tumor (continued). "Since imatinib preferentially targets mutant receptors, reduced drug responsiveness and aggressive GIST behavior may also reflect activation of WT KIT expressed in the majority of GIST by KITLG originating from the circulation, the tumor cells, or their niche." (PMID 24116170, 2013). "Immunohistochemical analysis revealed that the tumor cells were positive for KIT as well as CD34, and negative for alpha-smooth muscle actin and S-100 protein expression." (PMID 23606918, 2013). "Bulk profiling of tumour specimens suggests that only PDGFRA is common to 4q12 amplified cases, with 39% of these harbouring PDGFRA amplification alone, 23% including PDGFRA and KIT, and 38% encompassing all three RTKs." (PMID 23990986, 2013). "Unlike BRAF genotypes, KIT genotypes were poorly matched between primary tumours, metastases, and CTC." (PMID 22281663, 2012). "In KIT+ tumors, CD117 was expressed in the majority of cytokeratin+ tumor cells." (PMID 23285214, 2012). "This is consistent with the biology of thyroid neoplasia in people in which KIT dysregulation is not believed to be a contributory factor in tumor biology." (PMID 22630170, 2012). "The sole high CD117 expressor among the KIT “negative” tumor group was at the upper range of percent CD117+, suggesting transition or misclassification (red circles)." (PMID 23285214, 2012). "Immunofluorescence studies on FFPE tumor confirm the works of other, dividing tumors into KIT+ and KIT negative." (PMID 23285214, 2012). "A retrospective study of archival tumor specimens from patients with histologically confirmed HCC suggested that KIT is not significantly overexpressed in this tumor type." (PMID 21787417, 2011). "Phosphorylated KIT was moderately (++) or strongly (+++) expressed in endothelia of 10 (29%) tumors, but it was not expressed strongly in any of the cases in tumor cells." (PMID 20030644, 2010). "As KIT activation did not depend on the gain-of-function mutations, we looked for the presence of the KIT ligand SCF within the tumours." (PMID 16570044, 2006). "It has with direct anti-tumor as well as antiangiogenic activity via its multi-targeting process; the vascular endothelial growth factor (VEGF), platelet-derived growth factor (PDGF), KIT, and FLT3 receptor tyrosine kinases." (PMID 15854222, 2005). "The 5-year overall survival rates for patients with tumours with negative, weak positive and strong positive KIT expression were 50% (95% CI, 45–55%), 34% (19–50%) and 35% (3–66%), respectively." (PMID 15583695, 2004). "Comparative analyses showed both lack of correlation with the expression of the tumour progression associated ICAM-1 adhesion molecule and, in 23% of cases, co-expression with the c-KIT encoded receptor." (PMID 8104462, 1993). "Tyrosine kinase inhibitors (TKIs; e.g., imatinib, sunitinib, regorafenib, ripretinib) were hypothesized to block the constitutive activation of KIT- and PDGFRA-mediated pathways, and have indeed demonstrated anti-tumor activity in clinical trials of patients with advanced GIST." (PMID 41264161, 2026). "In sample-level scRNA-Seq correlations of tumours, FRC-like fibroblasts positively correlated with various B-cell subsets [including cycling B-cells, FCRL4 + B-cells and germinal centre (GC) B-cells], plasma cells, KIT + NK-cells, with high correlation with IgM expressing B/plasma cells." (PMID 39757146, 2025). "Among the variants identified, one, located in KIT, overlapped with genes associated with clonal hematopoesis of indeterminate potential (CHIP) and can therefore not be confidently associated as being of tumor origin." (PMID 40806740, 2025). "While tumours lacking variants in these genes but also BRAF/RAS and NF1 have been dubbed ‘quadruple wild-type’, it is more appropriate to specify those genes that have been tested, e.g. WT for KIT, PDGFRA, NF1 and BRAF/RAS." (PMID 38840030, 2025).
tumor (continued). "Molecular analysis of tumours from the patients included in the SSG XVIII study which compared 1 versus 3 years of adjuvant imatinib showed that the largest benefit was observed in those patients with otherwise poor prognosis, i.e. those with KIT exon 11 deletions or insertion/deletions, (indels)." (PMID 38840030, 2025). "Notably, the mice treated with KIT-d-MMAE showed no body weight loss or organ damage, further verifying that KIT-d-MMAE effectively inhibited tumor progress without any adverse effects." (PMID 40963922, 2025). "Mice in the KIT-d-MMAE group did not exhibit significant weight loss; conversely, the weight gain rate in the DPBS group was lower than in the KIT-d-MMAE group, possibly due to liver dysfunction caused by tumor metastasis." (PMID 40963922, 2025). "An immunohistochemical feature of LOT is that the tumor expresses KRT7 but not KIT." (PMID 39980061, 2025). "Depletion of KIT-positive cancer stem cells significantly reduces tumour growth in mice; however, it is important to note that the presence of KIT alone is not sufficient for tumour formation." (PMID 41511287, 2025). "One previous study associated the expression of c-KIT, VEGFR-2, and PDGFR-β and TOC antitumor response in vitro and several studies have investigated TOC antitumor response in vivo, without association with c-KIT, VEGFR-2, and PDGFR-β tumor expression." (PMID 39126006, 2024). "Five out of nine studies included AdCC cases, and only 2/9 studies revealed a significant correlation between c-KIT expression and negative prognostic factors, i.e., presence of perineural invasion, local regional recurrence, advanced tumor stage, distant metastasis, or decreased survival." (PMID 39858584, 2024). "A randomised, Phase 3 clinical trial of masitinib demonstrated it was effective at delaying tumour progression in dogs with recurrent or non-resectable grade II-III non-metastatic MCT (increased OS from 75 to 253 days), with the presence of KIT mutations showing an improved response." (PMID 38787171, 2024). "Thus, the G5/PDGFRA subgroup contains tumors with an amplification of PDGFRA with or without neighboring KIT and KDR RTK genes from the 4q12 chromosomal locus, and more rarely, a tumor with PDGFRA activating mutations without amplification." (PMID 38254850, 2024). "In our exploration of TK expression in feline malignancies, we found that while TKI expression has been investigated in 21 different tumor types, nearly half of these records are either single cases or merely report the lack of a single TK expression (KIT or EGFR)." (PMID 37835664, 2023). "Sorafenib is a multitarget inhibitor for suppressing tumor angiogenesis and proliferation, the targets including some serine/threonine kinases, such as C-Raf, wildtype B-Raf, and mutant B-Raf, as well as some receptor tyrosine kinases, such as VEGFR 1-3, PDGFR, and c-KIT." (PMID 37175611, 2023). "If the HαT test is positive, no BM biopsy may be required, unless KIT D816V is also detected in blood leukocytes and/or other indicators of a coexisting SM or other BM neoplasm are present." (PMID 37572755, 2023). "However, spleens from neither group developed tumor foci, instead presenting with scattered intense KIT positive staining consistent with the appearance of transformed huMCs, especially in spleens of mice injected with HMC-1.2 cells." (PMID 37025992, 2023). "Prominent tumor vasculature, and more obvious tumor vessels more likely to occur in the GIST with KIT exon 11 deletions, this is consistent with previous research and suggesting a relationship between the deletion of KIT exon 11 and biological behavior of aggression." (PMID 37645430, 2023). "Similarly, NN2101-DM1 was also found to inhibit the tumor growth in GIST both in vivo and in vitro, and exerted its effect regardless of KIT mutations." (PMID 37072770, 2023). "c‐KIT, a type III RTK, may be involved in thyroid cell differentiation and tumor progression." (PMID 37506147, 2023).
tumor (continued). "Neither KIT nor PDGFRA mutations were detected by Sanger sequencing; however, next-generation sequencing (NGS) identified an FGFR2-KIAA1217 gene fusion in the tumor tissue." (PMID 35978808, 2022). "Finally, the tumor was diagnosed as GCT on pathological assessment including immunohistochemical examination, as the tumor was positive for S-100 and negative for both KIT and Desmin." (PMID 34677732, 2022). "Tumor cells were immunoreactive for S100 but not for smooth muscle actin or KIT." (PMID 36221358, 2022). "This KIT staining was described as cytoplasmic and stippled within neoplastic spindle-shaped cells and/or multinucleate giant cells, but did not appear to correlate with the tumour being a FISS." (PMID 36290122, 2022). "Expression of KIT is not uniform across the tumor; the highest levels of KIT expression are seen at the leading edge of tissue invasion, indicating a key role it may have in promoting metastasis." (PMID 34441278, 2021). "However, the authors did not observe any correlations between c-KIT mRNA in blood and tumor grading, degree of neoplasm differentiation, or clinical prognosis." (PMID 33665215, 2021). "Based on the known predictive role of tyrosine kinase (KIT) and platelet-derived growth factor receptor α (PDGRA) tumor genotypes, the differential clinical response to first-line imatinib treatment might be related to the different types and gene locations of the mutations." (PMID 33673554, 2021). "Conversely, the need to identify alternative mechanisms of imatinib resistance in KIT-mutant GISTs showed that the activation of FGF/FGFR signaling pathway and the crosstalk with KIT receptor could represent a route for tumor cells to acquire secondary resistance towards imatinib." (PMID 32392832, 2020). "Although c-KIT protein overexpression may be correlated with more aggressive tumors, higher invasion capacity and tumor recurrence, heterogeneity and/or the absence of c-KIT protein expression has been demonstrated in the epithelial cells of human PC." (PMID 33324695, 2020). "Among the proteins of interest (NPM1, FLT3, DNMT3A, IDH1, IDH2, KIT, and RAS), non-mutation bearing ligands from NPM1 were the most frequent in both patient tumor samples and cell lines, including ligands close to or corresponding to where hotspot mutations occur (EAIQDLWQW and MTDQEAIQDLWQWR)." (PMID 31291378, 2019). "Remarkably, PDGFRα and KIT are expressed at much higher levels in the normal kidney than in the tumor cells, showing that targeting of ccRCC by sunitinib is not as cancer-specific as desirable, which may explain observed sunitinib-induced toxicity." (PMID 30881919, 2019). "Among the tumor-related genes, the top amplified genes included ERBB2 (17q21), MYC (8q24), GNAS (20q13), EGFR (7p11), ZNF217 (20q13), CCNE1(19q12), NCOA3 (20q13), and CDK6 (7q21), and the most frequently deleted genes were CDKN2A (9p21), CDKN2B (9p21), KIT (4q12), SMAD4 (18q21), and FGFR1 (8p12)." (PMID 31541076, 2019). "Also the reactivation of developmental processes initiated by stem cell factor (SCF)/KIT, and Wnt signaling may play a role in the therapeutic response of HNSCC tumor cells." (PMID 30259648, 2018). "In our case, because both the malignant components were negative for KIT, the tumor may not have been derived from stem cells." (PMID 29900476, 2018). "The Ki67 value was higher in c-KIT positive tumours than in c-KIT negative tumours." (PMID 29207991, 2017). "In addition, the tumor was negative for c-KIT and DOG-1 immunostaining and for a c-KIT gene mutation study." (PMID 28351362, 2017). "Tumor angiogenesis, required for malignancy, is under control of miRNAs: miR-221/222 are anti-angiogenic (through the stem cell factor (SCF) and KIT Proto-Oncogene Receptor Tyrosine Kinase (c-Kit) axis), while miR-27b, miR-130a, and miR-126, the last also termed angiomiR, are pro-angiogenic." (PMID 29485611, 2017).
tumor (continued). "Importantly, potency of crenolanib to inhibit cellular proliferation as well as to induce apoptosis of the engineered Ba/F3 cell strains (harboring KIT D816V, KIT D816Y or FLT3 ITD) revealed strong correlation with the corresponding tumor cell lines (HMC1.2, p815 or MOLM14, respectively)." (PMID 29137311, 2017). "The tumor cells were positive for PDGFRα and negative for KIT, DOG1, CD34, S100, and desmin." (PMID 27842558, 2016). "Indeed, depending on the tumor genotype, about half to three quarters of patients with advanced GIST respond to treatment with anti-KIT/PDGFRA tyrosine kinase inhibitors (TKIs) including the first-line drug, imatinib mesylate (Novartis Pharmaceuticals, Switzerland)." (PMID 27793025, 2016). "Given the absence of activating missense mutations that confer sunitinib sensitivity, the amplification of KIT, PDGFRA, and/or VEGFR2 may have represented the critical sunitinib target in our case and may explain the primary good response of the tumor to the drug." (PMID 26474454, 2015). "Several neutralizing antibodies or inhibitors against tumor-derived factors or those receptors such as GM-CSF, GM-CSF receptor (GM-CSFR), M-CSF, M-CSF receptor (M-CSFR), G-CSF, VEGF-A, or stem cell factor (SCF or KIT) have been reported to inhibit MDSC expansion or mobilization." (PMID 26078490, 2015). "In addition to KIT and KRAS, there was an over-representation of mutations in cell division cycle 27 (CDC27) (11.9%; 5 mutations, 5 tumours) and PRKRIR (4 mutations, 2 tumours), neither of which have been previously reported as TGCT drivers." (PMID 25609015, 2015). "In this study, we showed that treatment of GIST xenograft lines with nilotinib resulted in a decrease in tumor growth, suggesting that nilotinib-mediated growth inhibition in GIST might be occurring through interference with the activity of KIT or PDGFRA signaling pathways." (PMID 25221952, 2014). "Diagnosis of recurrent AF tumor with positive c-KIT and without hormonal receptor was retained." (PMID 25488584, 2014). "Furthermore, in contrast to the adjacent non-neoplastic liver that lacked KIT staining, the implanted tumor had strong KIT immunostaining signals." (PMID 24507750, 2014). "The tumor cell cytoplasm stained weakly for KIT, which is unusual (but not unknown) for GIST tumors." (PMID 24938355, 2014). "The CD4:CD8 ratio did not change after transduction or exposure to KIT+ tumor (not shown)." (PMID 23433424, 2013). "Furthermore, the primary duodenal GIST was reevaluated as borderline nature and no KIT and PDGFRA mutation was found in the tumor." (PMID 23902675, 2013). "Due to uncertainty about upfront surgical resectability, the patient was started on imatinib (400 mg/day), a tyrosine kinase inhibitor (TKI) that blocks the constitutively active receptor tyrosine kinase c-KIT, to induce adequate tumor response for potential surgical resection with negative margins." (PMID 23983708, 2013). "Cabozantinib has better effects on tumor angiogenesis and survival than those found with combinations of selective inhibitors of MET and VEGF signaling in the same model, suggesting that AXL or other targets (such as RET, KIT and TIE2) contribute to the efficacy of cabozantinib." (PMID 24213559, 2013). "The crucial issue appears to be whether tumors depend on KIT activity for their survival or growth, and not whether tumor cells merely express KIT." (PMID 23285214, 2012). "The role of c-KIT in human neoplasia is not fully cleared yet." (PMID 22233760, 2012). "They conclude that these observations likely account for the absence of correlation between response to imatinib and KIT expression using IHC and may deserve to be investigated in other tyrosine kinase-activated tumours." (PMID 20664593, 2010).
tumor (continued). "Since in each tumour, epithelial and spindle cell components harbour the same type of translocation t(X;18) the present findings suggest a shifting of the anti-apoptotic role from BCL2 to c-KIT gene during the transition from the uncommitted spindle to the differentiated epithelial cells." (PMID 11487273, 2001). "However, more data on the relationship of KIT overexpression and response to TKI in the setting of wild type KIT should be collected to assess whether the amount of wild type KIT transcript in a tumor could be utilized to predict the patient’s response to imatinib and other TKIs." (PMID 40119139, 2025). "Moreover, the pharmacological inhibition of c-KIT, the antibody-based inhibition of OX40L, or genetic ablation could be a potential future strategy to improve the anti-tumor activity of NK cells in response to therapeutic treatment with monoclonal antibodies, such as RTX." (PMID 39201666, 2024). "LOP628-emtansine (DM1) is sensitive in tumor cells with high KIT level, regardless of its mutational status, suggesting that this ADC may be used in the treatment of KIT-mutant and KIT-WT GIST, but the hypersensitivity reactions (HSRs) caused by LOP628-DM1 may constrain its usage in clinic." (PMID 37072770, 2023). "However, it is conceivable that oncogenic alterations in the KIT ectodomain that were not part of this molecular analysis might play a role in driving tumor growth, analogous to what has been observed for the ErbB family of receptor tyrosine kinases." (PMID 35050442, 2022). "Detectable c-KIT transcript in the primary tumour from which PC1 cells were derived and the absence of transcript in the respective cell line could be related with expression of c-KIT by stromal cells, since the cell line contains only neoplastic epithelial cells." (PMID 29207991, 2017). "Thus, it was considered that there was no oncogenic mutation in KIT and PDGFRA genes in this tumor." (PMID 28288693, 2017). "Results showed that expression of p55PIK was not changed; however, the expression of KIT and NF-κB pp65 (Ser536) was decreased, indicating that p55PIK signaling blockade inhibited the NF-κB signaling and KIT expression, which in turn, led to inhibition of tumor growth of IMA-resistance-GIST in vivo." (PMID 26587973, 2016). "Nevertheless, though we did detect significant increases of tumor suppressing microRNAs, miR-28 and miR-34a, their respective targets, HoxB3 and KIT, were not decreased, implying that miR-28-HoxB3 and miR-34a-KIT axes may not involve in the anti-CRC activities of Res." (PMID 26674205, 2015). "However, immunohistochemistry might not be sufficient to detect tumours with mutations susceptible for c-KIT blockade, as overexpression of c-KIT can also occur in tumours without mutation." (PMID 19018266, 2008). "Tumours with an immature granulocytic profile express CD34 and KIT (CD117), whereas CD34 is negative in tumours with a more mature profile." (PMID 39996833, 2025). "The tumor was histologically composed of oncocytic cells that expressed KRT7, vimentin, SDHA, SDHB and fumarate hydratase, but not KIT, GATA3 and alpha-methylacyl-CoA racemase." (PMID 39980061, 2025). "Among the tumor cell lines tested, MCA205, MC38, and EMT6 lacked expression of FLT3, c-KIT, and CSF1R." (PMID 39782686, 2025). "Together, these findings demonstrate that KIT-d-MMAE preferentially accumulates and persists in tumor tissue, while being rapidly cleared from circulation and normal organs, suggesting its potential for effective and low-toxicity targeted therapy." (PMID 40963922, 2025). "The IHC findings showed the spindle-shaped tumor cells that were positive for SMA, desmin, and negative for KIT, CD34 (data not shown)." (PMID 40625542, 2025). "Typically, tumor cells show positivity for vimentin, SMA, and H-caldesmon, while being negative for S-100 protein and c-KIT, supporting the diagnosis of PF." (PMID 38732067, 2024).